FGF21 (fibroblast growth factor 21)
Diseases named in the same sentence as FGF21 in open-access papers (continued):
Sharing a sentence is not in itself a finding about the gene and the disease.
Hepatic steatosis (continued). "FGF21 reverses liver steatosis by acting on hepatic lipid metabolism and glucose uptake, inducing thermogenesis in BAT and WAT, improving insulin sensitivity in muscles and liver, and increasing glucose uptake by adipose tissues." (PMID 34943946, 2021). "Exogenous Fgf21 therapy has also corrected IR and hepatic steatosis in diet-induced obese and ob/ob mice as well as diabetic rhesus monkeys." (PMID 34023388, 2021). "Since preclinical studies of FGF21 actions on liver steatosis were previously conducted only in males, more studies are needed to evaluate the efficacy of FGF21 in improving glucose metabolism and NAFLD in obese females." (PMID 34943946, 2021). "The development of fatty liver during early lactation is accompanied by an increased hepatic FGF21 expression and elevated blood FGF21 levels." (PMID 34517929, 2021). "Despite the reduced mitochondrial function in the liver, LSD1-LKO mice are protected from diet-induced hepatic steatosis and glucose intolerance, partially due to induction of hepatokine FGF21." (PMID 34314389, 2021). "FGF21 KO mice also presented with an increased incidence of fatty liver disease and very-low-density lipoprotein receptor levels via the activation of the eIF2a-activating transcription factor 4 (ATF4) pathway." (PMID 33498410, 2021). "Previously, we showed that the therapeutic effects of probiotic Lactobacillus rhamnoses GG (LGG) in mouse models of fatty liver diseases are mediated by FGF21/adiponectin upregulation." (PMID 34943840, 2021). "This accords with the finding that lower FGF-21 levels limit the protection against fatty liver disease, which is defined as a proinflammatory condition of steatohepatitis development that is identified through histologic analysis." (PMID 33401717, 2021). "Another easy-to-use and the precise system was designed using a MoS2-functionalized FET immunosensor for identifying Fibroblast growth factor 21 (FGF21)—a biomarker for fatty liver disease (NAFLD) detection." (PMID 33918325, 2021). "The FGF21-KO mice increased hepatic steatosis and low levels of lipoprotein receptor protein via the activation of the eIF2a-ATF4 pathway." (PMID 33498410, 2021). "Administration of FGF21, FGF21 analogs or adenoviral delivery of FGF21 reduces hepatic steatosis in diverse rodent models of NAFLD and NASH." (PMID 33381084, 2020). "The increase of energy expenditure promoted by irisin, through PPAR-α-dependent signaling, improves insulin sensitivity and reduces hepatic steatosis by upregulating FGF21." (PMID 32443765, 2020). "In Phase 2 clinical trials analogues of FGF19 and FGF21 decrease hepatic steatosis with up to 70% (MRI-PDFF) after 12 weeks and as early as 12–16 weeks of treatment an improvement in NASH resolution and fibrosis has been observed." (PMID 33414764, 2020). "In response to fasting, ketogenic diet, high fat diet, alcohol, and protein restriction the FGF21 ko mice develop liver steatosis." (PMID 33414764, 2020). "FGF19 requires KLB expression in the liver to regulate Cyp7a1 expression in mice, while the positive effect of FGF19 and FGF21 on hepatic steatosis was unaffected by adipose and liver specific KLB deletion." (PMID 33414764, 2020). "Clinical trials of FGF21 administration to NAFLD patients showed improvements in liver steatosis and fibrosis." (PMID 33102766, 2020). "Another study showed that canagliflozin, an SGLT-2 inhibitor, increased fatty acid oxidation, reduced hepatic steatosis, and increased plasma levels of FGF21." (PMID 32957703, 2020). "A decrease in the delivery of triglyceride-enriched very low-density lipoprotein (VLDL) to the liver by downregulating VLDL receptor expression has also been described as a mechanism by which FGF21 treatment lowers hepatic steatosis." (PMID 33414764, 2020).
Hepatic steatosis (continued). "More cases are required to validate our findings, including the BMI, FGF-21, γ-GT, and TG cut-off values for detecting high-grade liver steatosis in obese and overweight children and confirming the role of FGF-21 in clinical practice." (PMID 31750276, 2019). "The strength of this study lies in our thorough evaluation of different clinical and laboratory parameters and the inclusion of FGF-21 as part of a biomarker panel to predict liver steatosis severity." (PMID 31750276, 2019). "Our results demonstrated that γ-GT, FGF-21, and TG levels and BMI were strongly correlated with liver steatosis severity." (PMID 31750276, 2019). "Other investigational anti-fibrotic agents, such as FGF21 and metformin, display improvement in hepatic steatosis and a decrease in hepatic stiffness by an increase of insulin-sensitization and normalization of serum aminotransferases, respectively." (PMID 30642126, 2019). "The degree of alcoholic fatty liver was enhanced in liver-specific Fgf21 knockout mice; however, alcohol treatment increased the hepatic FGF21 expression level both in vitro and in vivo." (PMID 31405033, 2019). "Reduction of FGF21 level in mice on a ketogenic diet leads to hepatic steatosis, lipemia, and a decrease of serum ketone concentration." (PMID 30927227, 2019). "The present study involved a thorough evaluation of anthropometric data and body composition using different techniques and an examination of the correlation between biochemical markers, such as adipokines and FGF-21 levels, and liver steatosis severity." (PMID 31750276, 2019). "In rats, a high‐fat, high‐fructose diet results in sex‐specific differences in hepatic steatosis, inflammation and FGF21 expression." (PMID 31687174, 2019). "FGF21 has been shown to regulate AMPK phosphorylation in tissues other than pancreatic islets; for example, FGF21 treatment reversed alcoholic fatty liver and hepatic steatosis via activation of the hepatic AMPK-SIRT1 pathway." (PMID 31121855, 2019). "A large body of evidence showed that Hepatic steatosis, an underlying feature of non-alcoholic fatty liver disease (NAFLD), induced changes in FGF21 secretion." (PMID 30692965, 2018). "CREBH, activated by triglyceride accumulation, induces FGF21, which suppresses adipose tissue lipolysis, ameliorating hepatic steatosis." (PMID 29738435, 2018). "FGF21 production was impaired in CREBH KO mice, and adenoviral overexpression of FGF21 suppressed adipose tissue lipolysis and improved hepatic steatosis in these mice." (PMID 29738435, 2018). "Their body weight, glucose-lipid metabolism, inflammation indices, hepatic steatosis and fibroblast growth factor 21 (FGF21) levels were measured." (PMID 30355361, 2018). "FGF21 has been reported to reverse hepatic steatosis and improve insulin sensitivity in high -fat diet-induced obese mice." (PMID 29444136, 2018). "FGF-21, a liver-secret hormone, has recently been shown to possess beneficial effects on lipid metabolism and hepatic steatosis." (PMID 28326329, 2017). "Our findings suggest that FGF-21 showed excellent performance to distinguish NASH from hepatic steatosis." (PMID 28326329, 2017). "The data also revealed an approximate 4-fold induction of FGF21, and this growth factor is known to ameliorate hepatic steatosis." (PMID 29296203, 2017). "Remarkably, in patients with NASH and hepatic steatosis, serum FGF21 concentrations were notably elevated and correlated with the degree of steatosis, indicating its great utility as a serum biomarker for diagnosis." (PMID 28974056, 2017). "The present study provides evidence for the possible involvement of FGF21 signaling in the development of chronic alcohol-induced hepatic steatosis and injury." (PMID 27498701, 2016). "Hepatic steatosis was improved by FGF21 overexpression in Creb3l3−/− mice, as determined by decreased hepatic TG content and liver size." (PMID 27301791, 2016).
Hepatic steatosis (continued). "Serum FGF21 levels are significantly increased in patients with hepatic steatosis and NASH in a manner that is dependent on the degree of steatosis." (PMID 27148532, 2016). "With increased hepatic steatosis, expression and the acetylation levels of hepatic SREBP1c were found to be up-regulated in alcohol exposed FGF21 KO mice leading to enhanced gene expression and activation involved in fatty acid de novo synthesis." (PMID 27498701, 2016). "We sought to determine the role of FGF21 in hepatic steatosis in mice exposed to chronic alcohol treatment and to discern underlying mechanisms." (PMID 27498701, 2016). "A growing body of literatures show that exogenous FGF21 administration improve glucose and lipid homeostasis, insulin sensitivity and hepatic steatosis." (PMID 26914024, 2016). "The administration of a high dose of intravenous FGF21 reverses hepatic steatosis, improves insulin sensitivity, and decreases serum glucose levels in mice with NAFLD." (PMID 27148532, 2016). "Last but not least, to fully prove miR‐212 downregulation contributes to the protective effect of exercise against non‐alcoholic fatty liver via targeting FGF‐21, further study is required to subject miR‐212 transgenic mice to exercise training with HF diet." (PMID 26648452, 2016). "Forced FGF21 expression in partial hepatectomized hPPARαPAC mice reduced hepatic steatosis, prevented focal necrosis, and restored liver mass." (PMID 26701854, 2016). "Here we show that the liver-enriched transcription factor CREBH is activated by TG accumulation and induces FGF21, which suppresses adipose tissue lipolysis, ameliorating hepatic steatosis." (PMID 27301791, 2016). "Severe hepatic steatosis and inflammation in KD-fed CREBH deficient mice were substantially reversed by adenoviral overexpression of FGF21." (PMID 27301791, 2016). "The hepatic knockdown of FGF21 leads to a fatty liver and dyslipidemia, whereas the hepatic expression of FGF21 enhances hepatic lipid oxidation and TG clearance." (PMID 28025491, 2016). "Paradoxically, recombinant murine FGF21 treatment reverses hepatic steatosis by increasing energy expenditure in DIO mice." (PMID 27455076, 2016). "FGF21 confers multiple metabolic benefits, which include improving hyperglycemia, hyperlipidemia, hepatic steatosis, and obesity." (PMID 27301791, 2016). "FGF21 KO mice were subjected to chronic-binge alcohol exposure, and epididymal white adipose tissue lipolysis and liver steatosis were investigated." (PMID 26092866, 2015). "The beneficial effects of FGF21 on serum FFAs and the reduction in hepatic steatosis, however, were still present." (PMID 26834701, 2015). "Chronic treatment of obese rodents with FGF21 reduced hepatic steatosis and improved insulin sensitivity, indicating that FGF21 treatment also improves liver function." (PMID 26834701, 2015). "FGF21 is reported to be involved in various pathological conditions, including fatty liver disease, ER stress, and chronic inflammation, as discussed in this manuscript." (PMID 26441837, 2015). "FGF21 improves hepatic steatosis and insulin sensitivity in obese mice by stimulating lipolysis and fatty acid oxidation and reducing gluconeogenesis." (PMID 24935677, 2014). "After starvation for 48 hrs that induces hepatic steatosis, the expression of FGF21 was induced more than 220 fold exclusively in the liver, which was about 22 times that in the fed state." (PMID 23590285, 2013). "We, for the first time, demonstrated that BM extract attenuated hepatic steatosis in mice by enhancing hepatic FGF21 and AMPK/Sirt1 signaling." (PMID 24189525, 2013). "In all cases, elevation of FGF21 or treatment by FGF21 ameliorated hepatic steatosis and other abnormal hepatic metabolic parameters." (PMID 23590285, 2013). "A recent study showed that treatment of recombinant murine FGF21 exerts beneficial effects on hepatic steatosis." (PMID 21949781, 2011).
Hepatic steatosis (continued). "When the patients with severe hepatic steatosis (the fourth quartile) were included, the quantitative correlation between FGF21 and hepatic fat content was weakened." (PMID 21949781, 2011). "Since liver is the major site for FGF21 expression and hepatic steatosis is highly correlated with impairment of glucose and lipid metabolism in humans, the relationship between hepatic steatosis and FGF21 has been investigated in several recent studies." (PMID 21949781, 2011). "Within the range of hepatic steatosis from the first to third quartile, FGF21 was superior to any other traditional clinical markers including ALT to reflect hepatic fat content." (PMID 21949781, 2011). "Serum FGF21 concentrations were positively correlated with hepatic fat content especially in subjects with mild/moderate hepatic steatosis (r = 0.276, p = 0.009)." (PMID 21949781, 2011). "On the other hand, adenovirus-mediated down regulation of FGF-21 in the liver led to the development of fatty liver, dyslipidemia, and reduced serum ketones due to the altered expression of key genes involved in hepatic lipid and ketone metabolism." (PMID 21206918, 2010). "A secondary aim was to compare FGF-21 levels between patients with hepatic steatosis and NASH." (PMID 40465044, 2025). "In addition, the fibroblast activation protein (FAP) inhibitor BR103354 blocks FGF-21 degradation, significantly prolonging half-life of FGF-21 and improving metabolic phenotypes and hepatic steatosis in diabetic mice." (PMID 40437610, 2025). "The field has also witnessed the emergence of novel therapeutic strategies targeting the adipokine-hepatokine axis, with mechanistic studies elucidating the roles of key mediators like adiponectin, leptin, and FGF21 in hepatic steatosis, inflammation, and fibrosis." (PMID 40868109, 2025). "The mechanism by which theobromine intake may alleviate fatty liver involves its main components, like pyruvic acid, mimicking the action of fibroblast growth factor 21 (FGF21) and activating the FGF21 signaling pathway." (PMID 38839921, 2024). "We do not know if the FGF21 secretion is an early pathological change of hepatic steatosis per se, for liver damage might lead to increased FGF21 release." (PMID 38816541, 2024). "This increase in adiponectin may mediate the indirect effects of FGF21 analogs by enhancing peripheral energy intake and suppressing hepatic steatosis and inflammation." (PMID 39409124, 2024). "This could explain why studies have found that pharmacological interventions based on FGF21 analogs have reduced hepatic steatosis and improved several biomarkers of liver fibrosis in patients with NASH." (PMID 39409124, 2024). "However, DIO-MASH FGF15INT-KO mice showed a specific pathology involving the development of microvesicular hepatic steatosis and increased circulating FGF21 levels that should be further evaluated in the development of metabolic liver disease." (PMID 38587078, 2024). "Based on this combined knowledge, we suggest that by causing hepatic protein restriction, DB may have initiated a stress response resulting in FGF21 production by the liver, ultimately reducing hepatic steatosis." (PMID 39136056, 2024). "Moreover, the FGF21 signaling pathway mediates ketogenic diet-induced amelioration of hepatic steatosis." (PMID 39100807, 2024). "While the protective effect of pharmacological intervention with long-acting FGF21 on human liver steatosis has been uncovered, mechanisms underlying attenuated steatosis as well all the anti-inflammatory and anti-fibrotic effects of FGF21 on NASH are still largely unexplored." (PMID 36648330, 2023). "Based on the fact that CK18 is a marker of hepatocyte apoptosis and that FGF21 could be used as a marker of liver steatosis, this type of physical activity could act as method of prevention of NAFLD progression." (PMID 36902639, 2023). "Considerable ongoing interest in FGF21 stems from its beneficial actions on hepatic steatosis." (PMID 37249754, 2023).
Hepatic steatosis (continued). "Interestingly, two-phase 2a clinical trials reported that pharmacological FGF21 treatment improves liver steatosis in NASH patients." (PMID 36648330, 2023). "Among other functions, FGF21 increases the oxidation of fatty acids in the liver, reverses hepatic steatosis, and increases energy expenditure; in BD-exposed adolescent rats, its reduction is in concordance with the liver steatosis found." (PMID 37676577, 2023). "Then, we investigated the effects of FGF21 on liver steatosis, inflammation, and fibrosis." (PMID 36648330, 2023). "Particularly, patients with NAFLD, including fatty liver and steatohepatitis, have significantly higher serum FGF21 values than control subjects, which could prove useful for the non-invasive prediction of steatosis and fibrosis status in NAFLD." (PMID 35663311, 2022). "Furthermore, injection of recombinant FGF21 proteins into DIO mice reversed hepatic steatosis due to FGF21 inhibition of hepatic lipogenesis." (PMID 35517790, 2022). "We previously demonstrated that hepatic STAMP2 plays a pivotal role in preventing HFD-induced NAFLD and that both cilostazol and recombinant fibroblast growth factor 21 (FGF21) ameliorate HFD-induced hepatic steatosis by enhancing hepatic STAMP2 expression through AMPK." (PMID 36140186, 2022). "Therefore, the administration of FGF21 analogs has been shown to reverse hepatic steatosis in both mice and humans." (PMID 36457562, 2022). "In addition to improving hepatic steatosis in males, FGF21 decreases body weight and total body fat by increasing energy expenditure." (PMID 35998055, 2022). "Assessment of the NAFLD activity score (NAS) components revealed beneficial effects of FGF21 administration on hepatic steatosis, which was confirmed by a lower hepatic triglyceride content, while CCR2/5 inhibitor treatment was associated with reduced lobular inflammation." (PMID 35743140, 2022). "While FGF21 can affect the pathomechanism of these diseases, it can also play an important role as a biomarker for NAFLD and AFLD and show significant results in curing fatty liver and metabolic associated diseases." (PMID 36457562, 2022). "In addition, FGF21 agonists improve hepatic and systemic insulin sensitivity, leading to a reduction in hepatic steatosis." (PMID 36012166, 2022). "Reducing lipogenesis, inducing fatty acid β-oxidation, increasing hepatic insulin sensitivity, decreasing very-low-density lipoprotein (VLDL) transmission to the liver and subsiding the hepatic endoplasmic reticulum (ER) stress are the major mechanisms of FGF21 to improve fatty liver diseases." (PMID 36457562, 2022). "Others have exalted the importance of the epigenetic intervention of KBs on the liver, showing that the administration of sodium butyrate plays a protective role on hepatic steatosis through the epigenetically regulated increase in FGF-21 induced through the inhibition of class I HDAC3." (PMID 35956321, 2022). "Administration of FGF21 to mice was found to decrease hepatic steatosis." (PMID 34517929, 2021). "Anti-inflammatory effects of exogenous FGF21 were demonstrated to be mediated by an inhibition of nuclear factor-κB signaling pathway in different tissues, particularly under pathophysiological conditions, including mouse models of fatty liver." (PMID 34517929, 2021). "Another study showed that KLF15 can activate twist-related protein 2 (TWIST2) to ameliorate liver steatosis and inflammation by modulating nuclear factor (NF)-κB or sterol regulatory element-binding protein 1c (SREBP1c)-fibroblast growth factor 21 (FGF21) signaling pathways." (PMID 34299189, 2021). "We evaluated the metabolic phenotypes of LKO mice with global deficiency of GDF15 or FGF21 and show that GDF15 regulates body and fat mass and prevents diet-induced hepatic steatosis, whereas FGF21 upregulates insulin sensitivity, energy expenditure, and thermogenesis in white adipose tissue." (PMID 33718833, 2021).